TNF (tumor necrosis factor)
Diseases named in the same sentence as TNF in open-access papers (continued):
Sharing a sentence is not in itself a finding about the gene and the disease.
Obesity (continued). "Finally, the paths from %BF to autophagy and TNF-α are not significant (gray doted lines), supporting the hypothesis that CaSR and autophagy mediate the association between obesity (%BF) and expression of TNF-α in our model." (PMID 33076271, 2020). "Consequently, the accumulation of excessive macronutrients in the ATs in obesity, stimulates the release of inflammatory mediators like TNF-α and IL-6, causing the predisposition of the endothelium toward a proinflammatory state gearing to endothelial dysfunction." (PMID 32893859, 2020). "In addition, in the same study, propolis treatment for eight days restored adiponectin expression in TNF-α-treated, differentiated 3T3-L1 cells, suggesting the value of Brazilian red propolis as a diet supplement for prevention and treatment of obesity and obesity-associated disorders." (PMID 33383693, 2020). "Moreover, the inflammatory process that accompanies obesity and the associated increased levels of proinflammatory cytokines such as tumor necrosis factor α (TNF-α) may contribute to increased ceramide levels through activation of sphingomyelinase." (PMID 32375231, 2020). "Interestingly, FAM19A5 levels in human adipocytes were significantly downregulated by TNF-α-induced inflammation suggesting that pro-inflammatory cytokines produced during obesity may cause FAM19A5 downregulation." (PMID 33192583, 2020). "However, clinical studies have shown that blockade of TNF signaling alone is insufficient for improving insulin resistance or endothelial function in obese humans, suggesting that other pathways are involved in obesity-associated metabolic dysregulation." (PMID 33330676, 2020). "Furthermore, obesity is associated with abnormal TNF-α production of adipose tissues." (PMID 32218367, 2020). "However, the results of the presented study show that the impact of obesity and obesity-associated disturbances on DNA damage is strong and occurrence of obesity eliminates or significantly decreases the effect of the G-308A TNF-α variants on both inflammation, and levels of DNA damage." (PMID 30900134, 2020). "In recent decades, the involvement of many genes and polymorphisms in the pathogenesis of overweight/obesity have been hypothesized, such as: tumor necrosis factor-α (TNFα), interleukin (IL)-6, methylenetetrahydrofolate reductase (MTHFR) and fat mass and obesity-associated (FTO) gene." (PMID 31344895, 2019). "Additionally, ghrelin also plays roles in anti-inflammatory processes by repressing TNF-α-induced apoptosis and autophagy in adipocytes, so ghrelin may be beneficial for human obesity and obesity-associated type 2 diabetes." (PMID 31681009, 2019). "Obesity as a low-grade chronic inflammation has been associated with tissue hypoxia/necrosis with consecutively upregulation of the pro-inflammatory response via cellular (M1/2 macrophage—Th1/Th2 cells phenotype transformation) and molecular (IL-1β, IL-6, TNF-α) pathways." (PMID 30795781, 2019). "In addition, whether the regulation of TNFα signaling in type 2 diabetic cardiomyopathy linked to obesity is gender specific remains unknown." (PMID 30792662, 2019). "According to some hypotheses, the high levels of TNF that are commonly associated with obesity might lead to a hyper inflammatory state with a subsequent augmented risk of periodontal disease, although no strong evidence are available supporting this assumption." (PMID 30366466, 2018). "Inflammatory cytokines such as TNF-α may be associated with obesity-related IR." (PMID 30305178, 2018). "Increased oxidative stress and various pro-inflammatory cytokines and chemokines, including tumor necrosis factor-α (TNF-α) and interleukin-6 (IL-6), which might interfere with anti-inflammatory effects on insulin action, were associated with insulin resistance, obesity, and type 2 diabetes." (PMID 30532735, 2018).
Obesity (continued). "Severity of obesity is also associated with high blood pressure and is in part attributed to endothelial dysfunction, sympathetic nervous system overactivity, and fat cell inflammation contributing to increases in plasma interleukin-6 and tumor necrosis factor." (PMID 30009058, 2018). "The results of this study suggest that the G allele of rs361525 in the TNF-α gene may be a risk factor for overweight/obesity in the Korean population, with the frequency of the G/G genotype in the overweight/obese group being 9.3% higher than that in the control group (p= 0.0046)." (PMID 29696068, 2018). "In addition to regulate macrophage phenotypes, miR-155 mediates adipocyte dysfunction caused by inflammatory cytokines (e.g., TNF-α), which may contribute to the diet-induced obesity progression in C57BL/6 mice by limiting brown adipose tissue differentiation." (PMID 29899293, 2018). "Although the underlying mechanisms linking obesity to hepatic lipid accumulation and IR are incompletely understood, TNFα and IL-6 production in adipose tissue are critical for the development of steatohepatitis and NFκB has been recognized as an obligatory mediator of most of these TNFα responses." (PMID 29170528, 2017). "Obesity is also associated with elevated levels of proinflammatory cytokines in the circulation and in tissues, and thus, we found that IL-1β, IL-4, and TNF-α levels in the serum were increased in the HFD group, and all of the three supplements sufficiently reduced these levels." (PMID 29023387, 2017). "Additionally, 11β-HSDH1 knockout mice were demonstrated to be resistant to hyperglycemia caused by obesity and stress, and they were shown to have low resistin and TNF-α levels and high PPARγ and uncoupling protein 2 (UCP2) levels compared with these in the control." (PMID 28386270, 2017). "However, high levels of TNF-α in adipose tissue could account for any of the metabolic alterations associated with obesity such as insulin resistance." (PMID 27766104, 2016). "B. pseudocatenulatum CECT 7765 reduced obesity-associated systemic inflammation by restoring the balance between regulatory T cells (Tregs) and B lymphocytes and reducing pro-inflammatory cytokines of adaptive (IL-17A) and innate (TNF-α) immunity and endotoxemia." (PMID 26161548, 2015). "Obesity has been discovered to be associated with excess adipocyte hypertrophy generating a proinflammatory state through secretion of inflammatory cytokines and chemokines, including interleukin (IL)-1β, IL-6, IL-8, monocyte chemoattractant factor, tumor necrosis factor-α, and C-reactive protein." (PMID 26658675, 2015). "Obesity-associated inflammation occurs as a result of immune cell infiltration into the adipose tissue and increased production of pro-inflammatory cytokines such as IL–1β, IL–6 and TNF-α, leading to the pathogenesis of insulin resistance and eventually to the development of type 2 diabetes." (PMID 26437377, 2015). "Although the pathogenesis of obesity and its associated comorbidities are multifactorial, growing evidence suggests that altered production of adipose-derived protein factors (adipokines), such as leptin, tumour necrosis factor α (TNFα), adiponectin, and chemerin, plays an important role." (PMID 24665369, 2014). "Furthermore, TNF-α has also been associated with increasing the rate of atherosclerosis, a feature commonly increased in obesity, due to its ability to induce the expression of adhesion molecules in both endothelial cells and smooth muscle cells found in the vascular wall." (PMID 25309775, 2014). "Indeed, TNF-α has been established to be associated with insulin resistance, leading to obesity." (PMID 24324381, 2013). "Although it isn’t clear whether their anti-diabetic actions have any correlations with obesity-associated adipose tissue inflammation, some hypoglycemic triterpenes have been showed an effective inhibitory activity to TNF-α-induced insulin resistance and inflammation in hepatic cell FL83B." (PMID 24358329, 2013).
Obesity (continued). "In addition, PTP1B was suggested to be a key contributor to TNF-α-induced insulin resistance and inflammatory conditions in obesity by the other study showing that deficiency of PTP1B ameliorates pro-inflammatory TNF-α-induced insulin resistance and obesity-associated inflammation during aging." (PMID 23612372, 2013). "Therefore, our data suggested that neonatal overfeeding induced obesity may be a potential risk for lung fibrosis, which is related to inflammatory cytokine (TNF-α and TGF-β1) released by increased macrophages." (PMID 23056561, 2012). "Additionally, a positive association between TNF-α levels and neck circumference was observed in our study population while we did not manage to establish a correlation between this marker and other indices of obesity." (PMID 20628509, 2010). "Additionally, TNF-α is another factor that has been implicated in obesity-associated disorders." (PMID 19052637, 2008). "The relationships between TNFα receptors and plasma lipids in the obese group disappeared after controlling for insulin sensitivity, suggesting that lipid abnormalities associated with TNFα system in obesity might be fully explained by TNFα-associated insulin resistance." (PMID 16803616, 2006). "Individuals with obesity consistently show elevated circulating IL-6, TNF-α, and C-reactive protein (CRP)." (PMID 41543809, 2026). "In inflammatory settings, sinensetin attenuates NF-κB activation, lowers pro-inflammatory cytokines (e.g., TNF-α, IL-6), and enhances antioxidant defenses, supporting its reported antioxidant, anti-bacterial, anti-viral, and anti-obesity properties." (PMID 41597185, 2026). "The results showed that the proinflammatory cytokines IFN-γ and TNF-α had a significant association on CMI specifically in the older men with obesity of the G2 group, In addition, in the older women with obesity of G2 group, age showed an association with CMI." (PMID 41602164, 2026). "Obesity induces chronic low-grade inflammation, which increases the secretion of proinflammatory cytokines such as tumor necrosis factor α (TNF-α), and chemokines, such as GDF-15." (PMID 41597417, 2026). "Elevated levels of pro-inflammatory cytokines such as TNF-α, IL-1β, and IL-6 are observed in ovarian conditions including obesity, polycystic ovary syndrome, endometriosis, and reproductive aging." (PMID 41625246, 2026). "Mechanistically, type I inflammatory cytokines and obesity-associated molecules—including IFN-γ, TNF, leptin, insulin, and palmitate—induced PD-1 expression on macrophages through mTORC1- and glycolysis-dependent pathways." (PMID 41551882, 2026). "Obesity's chronic inflammatory milieu, with elevated IL-6, TNF-α, and CRP, compromises BBB integrity, facilitating immune cell infiltration and neuroinflammation." (PMID 41543809, 2026). "Consistent with previous studies, we found that obesity promoted a shift toward M1 macrophage dominance, characterized by increased circulating pro-inflammatory cytokines including TNF-α, IL-6, and IL-1β." (PMID 41556049, 2026). "The proteins that were increased in diabetes, including OSM, IL-8, IL-18R, TNFSF14, TNF and IL-6, play roles in obesity, insulin resistance, beta cell function and vascular diabetes complications." (PMID 41175199, 2026). "High-dose CU262 in particular brought IL-6/TNF-α down and IL-10 up relative to HFD alone (p < 0.05), indicating an attenuation of obesity-associated systemic inflammation." (PMID 41596930, 2026). "In the current study, obesity-induced inflammatory response was effectively ameliorated by exercise and YH administration by decreasing IL-1β and TNF-α levels." (PMID 40181294, 2025). "Obesity and metabolic syndrome are known to interact with the immune system, stimulating the production of pro-inflammatory cytokines, including TNFα and IL17A, with a potential synergistic role in promoting oxidative damage and telomere instability." (PMID 41249702, 2025).
Obesity (continued). "The hs-CRP and TNF-α levels correlated significantly better with the hematological and obesity-related indices, respectively." (PMID 40332236, 2025). "Given that obesity is a long-term inflammation potentially harming the liver, the presence of IL-1β, IL-6, and TNF-α in liver inflammation was identified using the ELISA kit." (PMID 39910919, 2025). "Pro-inflammatory cytokines (such as TNF-a and IL-6) derived from chronic low-grade inflammation in obesity can activate the coagulation system, leading to the release of clotting factors, which are intricately linked with tumour growth and progression." (PMID 40558305, 2025). "In obesity, adipose tissue hypertrophy leads to macrophage infiltration and the production of pro-inflammatory cytokines, such as TNF-α and IL-6, which play central roles in chronic inflammation and insulin resistance." (PMID 40862455, 2025). "One of the earliest and most critical alterations observed in obesity is hypothalamic inflammation, characterised by microglial activation, astrogliosis, and the secretion of proinflammatory cytokines such as TNF-α and IL-6." (PMID 41226484, 2025). "Obesity, particularly visceral adiposity, is characterized by chronic low-grade inflammation, driven by proinflammatory cytokines such as TNF-α and IL-6." (PMID 41001130, 2025). "Leptin, in particular, is implicated in the upregulation of inflammatory cytokines such as IL-6 and TNF-α, contributing to the low-grade inflammation characteristics of obesity." (PMID 39857920, 2025). "In obesity, the proliferation of adipose tissue accommodates elevated levels of proinflammatory immune cells (M1 macrophages, T cells) that release cytokines (TNF-α, IL-6, and IL-1β)." (PMID 40718355, 2025). "In contrast, two studies showed increased TNF‐α concentrations after vigorous intensity aerobic exercise in children with obesity and after a moderate intensity resistance training in prepubertal and pubertal boys." (PMID 40243109, 2025). "Semen samples from 272 male donors confirmed a correlation between obesity, sperm quality, and pro-inflammatory cytokine levels, showing elevated IL-6 and TNF-α in the semen of obese men, along with reduced sperm concentration and motility." (PMID 40564033, 2025). "In obesity, pro-inflammatory adipocytes-derived cytokines (IL-6, TNF-α, and IL-1β) and C-reactive protein (CRP) are often elevated." (PMID 41375608, 2025). "In individuals with obesity, adipose tissue becomes a source of inflammation, producing higher levels of proinflammatory markers like tumor necrosis factor-alpha (TNF-α), interleukin-6 (IL-6), and monocyte chemotactic protein-1." (PMID 40722684, 2025). "Obesity promotes a pro-inflammatory environment by increasing TNF-α, IL-6, IL-1, leptin, and resistin levels that reach the bloodstream and generate a systemic inflammatory state." (PMID 40067600, 2025). "The elevated secretion of TNF-α by adipose tissue can contribute to the development of many obesity-related complications, such as IR, hypertriglyceridemia, NAFLD or cardiac diseases." (PMID 40855499, 2025). "Psoriasis, a chronic systemic inflammatory disease, shares key pro-inflammatory mechanisms with obesity, including cytokines such as interferon-γ, interleukins, and TNF-α." (PMID 40358870, 2025). "Compared to normal-weight subjects, M1-type adipose tissue macrophages are specifically present in patients with obesity and induce an inflammatory response by secreting pro-inflammatory adipokines such as interleukin- 6, TNF-α, and nitric oxide." (PMID 40099262, 2025). "Consistently, IL36G expression was upregulated by hypoxia, inflammation-related factors (LPS, TNF-α and leptin) and by the adipocyte secretome from patients with obesity in HT-29 cancer cells." (PMID 40268791, 2025). "Research has shown elevated serum levels of IL-6 and TNF-α in both diabetes and obesity, with IL-6 and C-reactive protein (CRP) levels predicting the future onset of type 2 diabetes." (PMID 39852378, 2025).
Obesity (continued). "In individuals with obesity, adipose tissue becomes dysfunctional and secretes increased levels of pro-inflammatory proteins, such as interleukin (IL)-6, tumor necrosis factor alpha (TNF-α), C-reactive protein, and IL-18." (PMID 41150735, 2025). "Studies in both humans and animals have demonstrated that obesity-induced inflammatory changes in adipose tissue lead to elevated levels of proinflammatory cytokines, including TNF-α, IL-6, and monocyte chemoattractant protein-1 (MCP-1)." (PMID 40599559, 2025). "On the other hand, KLF-15 positively regulates CTRP12 adipocyte activity, reversing TNF-α-induced JNK dependence in obesity." (PMID 40427505, 2025). "Chronic inflammation in obesity contributes to this condition, as TNF-α and the suppressor of cytokine signaling 3 (SOCS3) pathways impair leptin signaling in the hypothalamus." (PMID 40862455, 2025). "Obesity, per se, induces TNF-α secretion, complicating attribution of elevated inflammation specifically to PCOS." (PMID 41561267, 2025). "This study aims to explore the combined role of ANGPTL3, 4, 8, omentin-1, leptin, TNF-α, and IL-6 molecules known for their roles in fat metabolism, obesity, and inflammation, yet whose connection to PCOS is still debated in the development of PCOS." (PMID 41341944, 2025). "Dense stroma‐induced hypoxia stabilizes HIF‐1α and, in concert with obesity‐related cytokines (such as IL‐6, TNF‐α, and leptin), activates the JAK/STAT3 pathway, upregulates PD‐1/PD‐L1 expression, and suppresses antigen presentation." (PMID 41267926, 2025). "Overnutrition and obesity heighten systemic inflammation through adipokines and free fatty acids (FFAs), promoting macrophage infiltration and secretion of cytokines like TNF‐α and IL‐1β." (PMID 40673471, 2025). "KEGG enrichment analysis results showed that the signaling pathways involved in ECT intervention in obesity mainly include the regulation of lipolysis, the TNF‐α inflammatory pathway, PPAR, and insulin resistance pathways." (PMID 40772014, 2025). "Focusing on the link between obesity and inflammation, we analyzed a possible correlation between TNF-α and FTO prostate expression." (PMID 40481981, 2025). "Pro-inflammatory macrophages, activated by obesity-related stress, secrete cytokines such as TNF-α and IL-6, which trigger the canonical NF-κB signaling cascade." (PMID 40282189, 2025). "Elevated TNF‐alpha expression in adipocytes of obese individuals correlates with obesity and hyperinsulinemia." (PMID 40551726, 2025). "Tabling the issue of obesity, it becomes apparent that higher levels of TNF-α, in obesity, result from increased macrophage infiltration into adipose tissue cells." (PMID 40244195, 2025). "This includes SNPs in genes such as the fat mass and obesity-associated (FTO) (rs9939609), melanocortin 4 receptor (MC4R) (rs17782313), tumor necrosis factor-alpha (TNF) (rs1800629), and IL6 (rs1800795)." (PMID 40278374, 2025). "Using CCJ12, in vivo effects on bodyweight, cholesterol, HDL, LDL, and triglycerides, leptin, adiponectin, sE-selectin, CRP, MCP-1 and TNF-alpha factors were studied in a high fat diet-induced obesity rodent model." (PMID 40770283, 2025). "Namely, in obesity, adipose tissue deposits release more pro-inflammatory cytokines and adipokines, including leptin and tumor necrosis factor alpha (TNF-α)." (PMID 40722842, 2025). "In conditions associated with inflammation (a common occurrence in cases of obesity and insulin resistance), the reduction in inflammatory cytokines (e.g., TNF-α, IL-6) that hinder insulin action can be attributed to SCFA production." (PMID 40650200, 2025). "In a cross-sectional study, Alzamil (2020) demonstrated that elevated serum TNF-α levels were strongly related to obesity and HbA1c levels in patients with type 2 diabetes mellitus." (PMID 40048497, 2025). "The TNF-α and IL-6 levels were high in participants with obesity, and diabetes with obesity, compared to control group." (PMID 40095937, 2025).